ISG15 (ISG15 ubiquitin like modifier)
Diseases named in the same sentence as ISG15 in open-access papers (continued):
Sharing a sentence is not in itself a finding about the gene and the disease.
tumor (continued). "Since we demonstrated that RT improved anti-tumor cytotoxicity of PBMCs, the irradiation marker ISG15 was measured and it increased in irradiated A549 in a dose-dependent manner (p < 0.001)." (PMID 34685495, 2021). "In this review, we discuss how ISG15 regulates viral replication, inflammation, cell proliferation and differentiation, and tumor genesis and development by modifying these proteins." (PMID 34901029, 2021). "We further examined the expression of known tumor-promoting markers in these immune subpopulations, confirming that CD4_CXCL13, CD4_FOXP3, CD8_CXCL13, CD8_ISG15, Mac_C1QA, Mac_ISG15 and Mac_SPP1 cells were tumor-promoting immune cells." (PMID 35087839, 2021). "Research results show that the tumor-suppressing function of unconjugated ISG15 is mainly related to its immune regulatory function." (PMID 34901029, 2021). "Results exhibited that both WT and Mut ISG15 suppressed the growth of SKOV3/DDP xenografted tumours in nude mice." (PMID 33797839, 2021). "Pincetic and Okumura demonstrated that ISG15 inhibited the monoubiquitination of the HIV group-specific antigen protein, blocked its interaction with host tumor susceptibility gene 101, and inhibited the emergence and release of HIV." (PMID 34901029, 2021). "ISG15, CDC20, TTK, and NCAPG expression showed positive correlations with tumor mutational burden and neoantigen load in BC patients." (PMID 34733851, 2021). "Both unconjugated and conjugated ISG15 have demonstrated tumor-suppressing and cancer-promoting functions." (PMID 34901029, 2021). "High ISG15 has been shown to be accompanied by certain oncogenic proteins facilitating tumour oncogenesis by inhibiting cells that control apoptosis in both primary tumour (with high α and β interferons) and during metastasis (when the interferons decrease)." (PMID 33073304, 2021). "The ubiquitin‐like protein interferon‐stimulated gene 15 (ISG15) is possibly dependent on tumour context to promote or suppress progression of various tumours." (PMID 33797839, 2021). "ISG15 expression was negatively correlated with tumor purity in basal-like BC, as well as with levels of infiltrating T cells, neutrophils, and dendritic cells; its correlation with tumor purity in the luminal subtype was undefined." (PMID 34733851, 2021). "The pathway analysis showed the involvement of the selected proteins in biological processes directly associated with tumor evolution (SEMA3A, BMP6, MDK), hepatitis viral infection (ISG15), or physiological liver functions (PLTP)." (PMID 35008303, 2021). "ISG15 has been reported to play a significant role in tumour microenvironment via enhancing T cells, B cells and epithelial cell lines cytokines." (PMID 33073304, 2021). "It was reported that ISG15 pathway induces BC cell conformational change leading to increase the tumour cell motility and metastatic ability through F-actin and microtubule filament modulation." (PMID 33073304, 2021). "DEG analysis revealed unique gene signatures for B cell clusters in tumour samples, including B_C5_ISG15 with interferon induced genes, B_C6_HSPA1A with stressful gene expression, and Plasma_C2_IgG with elevated expression level of IgH genes." (PMID 33531485, 2021). "A previous study that has investigated the role of ISG15 in tumour progression and invasion suggested that high expression of ISG15 enhances the cancer cell migration invasion and metastasis." (PMID 33073304, 2021).
tumor (continued). "Analysis of the 490 commonly overexpressed genes identified over-represented gene ontology (GO) terms associated with epithelial cell migration which highlights the role of ISG15 in tumour oncogenesis." (PMID 33073304, 2021). "To find new potential checkpoints, we investigated the cell-cell communications between tumor-promoting immune cells (CD4_CXCL13, CD4_FOXP3, CD8_CXCL13, CD8_ISG15, Mac_C1QA, Mac_ISG15, Mac_SPP1 and cDC3_LAMP3) and the ductal epithelial cells." (PMID 35087839, 2021). "ISG15 secreted by tumor cells increases tumor cell migration and immune escape by inducing M2 macrophage polarization." (PMID 34868310, 2021). "The ISG15 transcription is abnormally expressed in most human malignancies and exerts both pro- or anti-tumor functions." (PMID 33123466, 2020). "Together, our findings suggested tumor cell-secreted ISG15, which acted as a tumor microenvironmental factor, induces M2-like phenotype, promoting tumor progression and suppression of cytotoxic T lymphocyte response." (PMID 33424843, 2020). "For all data sets, ISG15 mRNA levels were significantly elevated in tumor samples or metastases versus adjacent normal tissue." (PMID 32472071, 2020). "The total frequency of ISG15+ CD163+ cells in suspension of NPC tissues varied from 1% to 9.7% among all live cells in the tumor microenvironment." (PMID 33424843, 2020). "Quantitative analysis of the tumour necrosis area showed that the Exo-ISG15 group had the largest area (62.1%) and that the Sh-ISG15 group had the smallest area (6.3%)." (PMID 32641707, 2020). "ISG15 is considered as a tumor biomarker due to its high level of expression as confined to tumors, and sensitivity to the anti-cancer drug camptothecin (Topotecan)." (PMID 33123466, 2020). "Further study indicated ISG15 can be secreted by NPC cells and expressed on the macrophages in NPC tissues, suggesting the regulatory role of ISG15 on tumor-associated macrophages." (PMID 33424843, 2020). "ISG15 nuclear staining was closely related to tumour size (P = 0.021), pTNM stage (P = 0.011) and lymphatic metastasis (P = 0.025)." (PMID 32641707, 2020). "Tumor cells secrete ISG15, and ISG15-activated TAMs promote cancer cell migration which develops a feed-forward loop between NPC cells and TAMs." (PMID 33424843, 2020). "In the Sh-ISG15 group, tumours had the fastest growth rate and had the largest weight compared to the control group." (PMID 32641707, 2020). "We observed the staining of individual tumor cells in 51% of the cases (20 of 39) for ISG15 (red arrows)." (PMID 31903170, 2019). "Here, we determined the key role of ISG15 in the tumor promoting properties conferred by L1 in human CRC cells and tissue." (PMID 31903170, 2019). "The next genes is ISG15 (Interferon-stimulated gene 15) another interferon, that is also from innate immune system and it is active in tumor inhibition." (PMID 30949322, 2019). "For instance, free ISG15 can exert an antitumor response by activating the innate and adaptive immunity at the tumor site." (PMID 30987352, 2019). "It was demonstrated that ISG15 was differentially expressed in different tumor cells and different cell lines from same histologic origin." (PMID 31309113, 2019). "In conclusion, the present study demonstrates that covalent ISG15 conjugation produces a novel CHIP regulatory mode that enhances the tumor-suppressive activity of CHIP, thereby contributing to the antitumor effect of type I IFN." (PMID 29367604, 2018). "The results showed a significant increase in tumor burden in mice injected with OVCA432 cells transduced with the ISG15 specific shRNA c22 when compared with scrambles shRNA transduced control mice (p = 0.023)." (PMID 30469497, 2018). "The results showed a significant correlation between ISG15 expression levels in tumor cells and NK cell densities." (PMID 30469497, 2018).
tumor (continued). "The results showed a significant decrease in tumor size in mice injected with ISG15 transduced cancer cells when compared to those injected with the mock-transduced cells." (PMID 30469497, 2018). "The results demonstrated a significant decrease in tumor weight in ISG15 treated mice when compared to those in PBS treated mice (p = 0.02)." (PMID 30469497, 2018). "In some studies, ISG15 functioned as a tumor suppressor as its expression was increased by antineoplastic agents like all-trans-retinoic." (PMID 27980214, 2017). "Taken together, we proved that ISG15 downregulation activated the DNA damage/repair pathway to enhance cisplatin resistance in tumor cells." (PMID 29296177, 2017). "Recently, knockout of ISG15 was shown to suppress K-ras-induced lung tumour as well as V-Src-mediated tumour formation in mice." (PMID 27545325, 2016). "The expression of ISG15 has been implicated in the regulation of type I IFN expression and the activation of NK cells, both of which are important mediators of tumor immunity." (PMID 27626310, 2016). "The siRNA-mediated knockdown of ISG15 expression inhibited tumor progression and increased survival in mice with xenograft tumors, demonstrating that ISG15 promotes HCC tumorigenesis and metastasis." (PMID 27626310, 2016). "The biological function of ISG15 promoting or suppressing tumor growth remains controversial and antagonistic roles of ISG15 in tumorigenesis have been reported." (PMID 27626177, 2016). "Whereas, ISG15 expression was correlated with tumor recurrence because high expression of ISG15 was more frequent in the NPC recurrence group than in the non-recurrence group (P<0.05)." (PMID 26919245, 2016). "Future studies of stage-specific changes in type I IFN expression, ISG15 expression, and ISGylation are needed to further clarify the role of ISG15 in innate tumor immunity." (PMID 27626310, 2016). "The expression of ISG15 has been implicated in the induction of type I IFN expression and the activation of NK cells, which are important mediators of tumor immunity." (PMID 27888627, 2016). "Our observation suggests that tumor cells expressing ISG15 enhance the CSC features of cancer cells." (PMID 26919245, 2016). "Several studies have demonstrated that ISG15 is an oncoprotein, as ISG15 gene expression and its protein conjugates were found elevated in tumor cell lines and in various human malignancies." (PMID 27626177, 2016). "In summary, we provided a novel line of evidence showing that ISG15 is an endogenous tumor suppressor." (PMID 27659523, 2016). "At the end of the experiment, the tumor sizes from ISG15-expressing HeLa cells were markedly smaller than those of the mock ones and the average tumor weight was significantly smaller in ISG15-expressing group." (PMID 27659523, 2016). "We also found increased NK cell staining in MDA/LV-control xenografted tumor sections (overexpressing ISG15) in mice administered with free ISG15 (third panel)." (PMID 25749047, 2015). "The same tumor sections were also stained in parallel with murine ISG15-specific antibodies, which demonstrated significantly ablated ISG15 signal in ZR/ISG15 shRNA compared to ZR/control shRNA xenografts." (PMID 25749047, 2015). "On the same day, recombinant purified free ISG15 (188 μg/animal; Boston Biochemical) was injected subcutaneously near the site of tumor implantation." (PMID 25749047, 2015). "We evaluated the extent of NK cell infiltration in ZR/LV-control and -ISG15 shRNA tumor sections by immunohistochemical analysis using the anti-NK cell-specific antibody DX5 (anti-CD49b-DX5 clone)." (PMID 25749047, 2015). "Conjugated ISG15 has been suggested to promote tumorigenesis, whereas free ISG15 is tumor suppressive." (PMID 26506425, 2015). "The average size of the ISG15 overexpressing tumors (66 mm in 3 weeks) was significantly lower than the ISG15-silenced tumors, measured three weeks post-implantation of tumor cells into nude mice (126 mm in 3 weeks) (P = 0.033)." (PMID 25749047, 2015).
tumor (continued). "Our results also explain why NK-dependent tumor regression remained unaffected in ISG15 knockout mice in a previously published study." (PMID 25749047, 2015). "On the other hand, a significant amount of NK cell positive staining was observed in MDA/LV-control shRNA tumor xenograft tissue sections (overexpressing ISG15), suggestive of the increased NK cell infiltration into these tumors (second panel, arrows)." (PMID 25749047, 2015). "Extracellular free ISG15 is an immune cytokine, and a chemotactic agent, whereas intracellular free ISG15 has been identified as a potential tumor antigen." (PMID 25749047, 2015). "Tumor cells deregulate the function of free ISG15, probably by blocking its secretion by conjugating it to cellular proteins consequently, escaping immune surveillance." (PMID 25749047, 2015). "To determine the in vivo effects of knocking down ISG15 on tumor growth, we established xenografted tumor models by subcutaneously injecting 97L or HepG2 cells into the back of BALB/c nude mice." (PMID 25238261, 2014). "Unlike ubiquitin whose expression is more or less constant in all cells, the ISG15 protein is highly expressed in the majority of tumor cells." (PMID 25238261, 2014). "Silencing ISG15 significantly inhibited subcutaneous tumor growth compared with the control groups by injection of the empty vector." (PMID 25238261, 2014). "ISG15 protein levels were also examined in the HCC specimens, among which 84% (42/50) of the cases showed relatively higher ISG15 expression than in the non-tumor counterparts (0.88 ± 0.07 vs. 0.50 ± 0.04, P < 0.001)." (PMID 25238261, 2014). "Knowing down ISG15 with SiRNA inhibited the xenografted tumor growth and prolonged the lifespan of tumor-bearing mice." (PMID 25238261, 2014). "Initially, ISG15 has been identified as ubiquitin cross-reactive protein (UCRP) in mouse tumor cells and it shares an amino acid sequence identity of about 30% with ubiquitin." (PMID 22693631, 2012). "ISG15 has been shown to be upregulated upon type I interferon stimulation, microbial infections and tumor growth." (PMID 21992229, 2011). "Most notably, ISG15 (interferon-stimulated gene 15), has been shown to be a new tumor marker for many cancers." (PMID 21897875, 2011). "Unlike ubiquitin whose expression is more or less constant in all cells, ISG15, which is undetectable in most normal tissues, is highly expressed, albeit with a high degree of heterogeneity, in both tumor cell lines and tumor biopsies." (PMID 21897875, 2011). "In order to determine the molecular basis for ISG15 up-regulation in tumor cells, we have evaluated the effect of oncogenes on ISG15 expression in cultured mammalian cells." (PMID 21897875, 2011). "Previous studies have demonstrated that ISG15 is highly, but variably, overexpressed in tumor tissues and tumor cell lines." (PMID 21897875, 2011). "It is possible that the increased ISG15 expressionthat accompanies proliferation induced telomere shortening functions to createan internal or external environment that restricts tumor progression." (PMID 20157543, 2009). "Enhanced ISGylation was observed in response to cancer chemotherapeutics, suggesting that ISG15 has a tumour-suppressing function." (PMID 18627608, 2008). "Consistent with this view, alterations in the ISG15 pathway have been identified in human tumours and in tumour cell lines." (PMID 18627608, 2008). "Patients who showed abundant ISG15 expression in the tumour had an estimated mean RFS of 112 months (95% confidence interval [CI]: 99 to 125) compared with 78 months (95% CI: 68 to 87) in patients with negative/weak ISG15 expression." (PMID 18627608, 2008). "At the protein level as determined by immunohistochemistry ISG15 was overexpressed in the tumour and correlated with upregulation of ISG15 mRNA." (PMID 18627608, 2008). "The median change in the tumour was three-fold compared with normal breast tissue on ISG15 mRNA level." (PMID 18627608, 2008).
tumor (continued). "The mean IRS score was 3.5 with 83.9% (n = 542) of tumours having a low score of zero to four and 16.1% (n = 104) showing abundant expression of ISG15 (IRS > 4)." (PMID 18627608, 2008). "In good agreement with the microarray results, the level of ISG15 protein was also increased in tumours." (PMID 16641915, 2006). "In total, ISG15 expression was analysed in both complete biopsy samples (four Ta, and five T2–T4 tumours), and in tissue microarray samples (20 Ta, and 20 T2–T4 tumours)." (PMID 16641915, 2006). "The median expression of ISG15 transcripts increased in 93% (26 out of 28) of the Ta tumours, 100% (20 out of 20) of the T1 tumours, and 98% (44 out of 45) of the T2–T4 compared to the median expression of the 18 normal tissue samples." (PMID 16641915, 2006). "Western blot analysis of these samples revealed that, similar to the comparison of ISG15 expression in normal individuals and cancer patients, unconjugated ISG15 was increased in tumour as compared to normal urothelium from the same patient." (PMID 16641915, 2006). "The ISG15 protein levels increased 4.1-fold in Ta and T1 tumours, and as much as a 12.1-fold increase in T2–T4 tumours." (PMID 16641915, 2006). "The tissue microarray analysis of ISG15 expression revealed that the fraction of ISG15-positive samples was increased in the groups of Ta and T2–T4 tumours compared to normal urothelium." (PMID 16641915, 2006). "One hundred per cent of T2–T4 tumours stained positive for ISG15, whereas only approximately 40% of the normal samples stained for ISG15." (PMID 16641915, 2006). "Consequently, in vitro co-culture assays and in vivo experiments reveal that SEMA6A overexpression in tumor cells enhances CD8+ T cell cytotoxicity via blocking the ISG15/TGFβ axis." (PMID 42303907, 2026). "ISG15 may regulate the tumor microenvironment by modulating PD-L1 stability, thereby influencing the effectiveness of immunotherapy." (PMID 41193953, 2025). "Moreover, we explored ISG15 protein expression in normal and tumor tissues from diverse human organs utilizing the HPA, and similar results were observed." (PMID 40208307, 2025). "Similarly, cells in immune_2 and immune_1, which are surrounded by tumor and stroma, respectively, have distinct expression patterns of marker genes such as ISG15, IFI6, and IFI27." (PMID 39960663, 2025). "Prior studies suggest that ISG15 may serve as a promising immunomodulatory to modulate the TME towards inhibiting tumor direction." (PMID 40904511, 2025). "The ubiquitin-like protein ISG15 has been thought to be a central player in the host antiviral response, and it is highly expressed in cancer stem cells and promotes tumor growth; however, whether ISG15 controls SSC proliferation remains to be investigated." (PMID 40151319, 2025). "Since some other cancers have demonstrated ISG15 protein overexpression in tumor-tissue, further studies are warranted to investigate whether peripheral blood ISG15 mRNA level is also prognostic in other cancer types." (PMID 40936712, 2025). "Increasing ISG15+ cells were detected in both the tumour region and normal bowel wall of patients with partial response for ICI treatment, whereas ISG15+ CD68+ macrophages were only enriched in the normal bowel wall, indicating their proinflammatory phenotypes in the bowel wall." (PMID 39934971, 2025).